ISG15 (ISG15 ubiquitin like modifier)
Diseases named in the same sentence as ISG15 in open-access papers (continued):
Sharing a sentence is not in itself a finding about the gene and the disease.
Autoimmunity (8 papers, 2016 to 2022). The occurrence of an immune reaction against the organism's own cells or tissues. "Autoantibody screening in peripheral blood was repeated for the boy at that age, since autoimmunity may develop later in the course of ISG15 deficiency." (PMID 34847081, 2022). "ISG15 has emerged as an abundant and versatile post-translational modification not only in the context of infection, but also in a range of stress conditions such as metabolic disorders, DNA damage, autoimmunity and inflammatory diseases." (PMID 36416643, 2022). "Thus, ISG15-secreting PCs represent a distinct proinflammatory PC subset providing an Ig-independent mechanism of PC action in human autoimmunity." (PMID 27357150, 2016). "These serum Ig isotyping, cytokine, chemokine, and ISG15 results are indicative of excessive inflammatory responses in Clec16aΔUBC mice and indicate a role for CLEC16A in autoimmunity." (PMID 33795715, 2021). "m6A elements (FTO, YTHDF2, YTHDF3, or YTHDC2) might target ISG15, stimulate the expression of ISG15, and activate the type I IFN signaling pathway, playing an active role in initiating the autoimmunity in pSS." (PMID 36465909, 2022).
dermatomyositis (8 papers, 2013 to 2025). Dermatomyositis (DM) is a type of idiopathic inflammatory myopathy characterized by evocative skin lesions and symmetrical proximal muscle weakness. "As a result, M2 macrophages were positively associated with the expression of IFIT3, OAS3, ISG15, and RSAD2 in patients with inflammatory cardiomyopathy and dermatomyositis, respectively." (PMID 37118825, 2023). "In one study, ISG15, IFIT3, OAS3, and RSAD2 were prominently enriched in the type I IFN signaling pathway, serving as central hub genes associated with myocarditis-related immune processes, suggesting their potential involvement in the mechanism of myocardial injury in dermatomyositis." (PMID 38753730, 2024). "Type 1 IFN-inducible genes, including ISG15, are highly upregulated in muscle, blood, and skin of patients with dermatomyositis (DM), an autoimmune disease affecting skeletal muscle and other tissues." (PMID 23750257, 2013). "This miRNA appears to regulate genes enriched in type I interferon signaling pathways (IFIT3, OAS3, ISG15, and RSAD2), which correlate with increased M2 macrophage infiltration in both dermatomyositis and myocarditis." (PMID 40433545, 2025). "In dermatomyositis, both USP18 and ISG15 are upregulated in inflamed muscle tissue regions." (PMID 37002195, 2023). "These sustained effects of IFN-β on myotube development, together with transcriptional data indicating sustained effects of IFN-β on ISG15 upregulation and recent findings implicating IFN-β in the pathogenesis of dermatomyositis, led us to focus further experiments on IFN-β alone." (PMID 23750257, 2013). "IFN-beta affects myoblast differentiation ability and myotube morphology in vitro.These studies provide evidence that ISG15, which is highly upregulated in dermatomyositis muscle, does not appear to play a key role in IFN-beta-mediated C2C12 myoblast cell fusion." (PMID 23750257, 2013).
Listeria infection (8 papers, 2015 to 2025). "Hyper-ISGylation is as protective against Listeria infection as wild-type ISGylation in tissue culture cells in contrast to Isg15-deficient fibroblasts, which are highly susceptible to Listeria infection." (PMID 31772204, 2019). "ISG15-deficient mice exhibited a significant increase in bacterial load compared to wild-type animals in both the spleen and liver after 72 hr of systemic sub-lethal Listeria infection." (PMID 26259872, 2015). "We next examined whether ISG15 could also play a role during Listeria infection in vivo by assessing the susceptibility of Isg15−/− animals to the pathogen during systemic infection." (PMID 26259872, 2015). "During Listeria monocytogenes infection, the expression of ISG15 is induced and ISG15 counteracts bacterial replication in an ISGylation-dependent manner both in vitro and in vivo." (PMID 40627782, 2025). "During Listeria monocytogenes infection, the expression of ISG15 increases, which depends on the cytosolic DNA-sensing pathway, and enhanced secretion of IL-6 and IL-8 was detected in ISG15-overexpressing cells." (PMID 34901029, 2021). "In particular, ISG15 expression is known to be induced independently of IFN-I/III signaling upon Listeria infection and its product, the ubiquitin-like modifier ISG15, inhibits Listeria infection in fibroblasts." (PMID 34858876, 2021). "Since USP18 is concomitantly induced with ISG15 following Listeria infection, we suspect that certain substrates are deconjugated more rapidly than others." (PMID 31772204, 2019). "We highlight sites that arise during Listeria infection in wild-type animals, as well as in mice with enhanced ISGylation due to knock in of an inactive ISG15 deconjugase (USP18C61A/C61A)." (PMID 31772204, 2019). "Together, these data indicate a tissue-specific role for ISGylation in the liver upon Listeria infection, and provided a rationale to map ISG15 sites in the liver of USP18C61A/C61A animals compared with wild-type animals." (PMID 31772204, 2019). "Most importantly, we were able to identify 614 ISG15 sites on 292 proteins induced by Listeria infection (cluster 2)." (PMID 31772204, 2019). "Most importantly, we demonstrate that ISG15 counteracts Listeria infection both in vitro and in vivo." (PMID 26259872, 2015). "Collectively, our data reveal that during Listeria infection ISG15 modification of distinct ER and Golgi proteins increases secretion of cytokines which are known to counteract infection in vivo." (PMID 26259872, 2015). "Most importantly, we observed that ISG15 expression restricts Listeria infection in vitro and in vivo." (PMID 26259872, 2015). "After 72 hr of systemic sub-lethal Listeria infection in mice, there was a robust induction of ISG15 and ISGylated conjugates in infected liver tissue, revealing that Listeria infection leads to ISG15 induction both in vitro and in vivo." (PMID 26259872, 2015). "Strikingly in the U5A cells (defective for type I interferon binding and signaling), as in 2fTGH cells, there is still a robust ISG15 response to Listeria infection." (PMID 26259872, 2015). "Taken together, these data demonstrate that ISG15 restricts Listeria infection both in vitro and in vivo." (PMID 26259872, 2015). "Together, our data reveal a previously uncharacterized ISG15-dependent restriction of Listeria infection, reinforcing the view that ISG15 is a key component of the innate immune response." (PMID 26259872, 2015). "They further showed that RNF213 acted as a binding protein for ISG15 and localized at the bacterial surface to exert an antibacterial effect, whereas other researchers have observed that ISG15 expression could restrict Listeria infection in vitro and in vivo." (PMID 37655297, 2023). "Given the particular relevance of these proteins in the control of autophagy, we explored whether this pathway is altered by ISG15 upon Listeria infection." (PMID 31772204, 2019).
Listeria infection (continued). "USP18 is concomitantly upregulated with ISG15 following Listeria infection and whether this is to temporally regulate specific targets or to alter STAT signaling remains to be determined." (PMID 31772204, 2019). "However, ISG15 can also be produced during bacterial listeriosis in a type I IFN–independent manner." (PMID 29891555, 2018). "Therefore, ISG15 appears to be a critical modulator of cytokine secretion following Listeria infection." (PMID 26259872, 2015). "Here again we could validate the endogenous modification of RTN4 by ISG15 following Listeria infection by detecting multiple distinct slower migrating bands of RTN4 and ISG15." (PMID 26259872, 2015). "This concomitant induction led us to hypothesize that ISG15 could be induced in an interferon-independent manner during Listeria infection." (PMID 26259872, 2015). "Finally, our proteomic analysis has helped to reveal a novel mechanism through which ISG15 and ISGylation can restrict Listeria infection." (PMID 26259872, 2015). "Furthermore, we assessed cytokine secretion in transformed MEFs that lack ISG15, relative to their wild type counterparts following Listeria infection." (PMID 26259872, 2015). "We hypothesized that the massive induction of ISG15 following Listeria infection must have a phenotypic effect on host cells." (PMID 26259872, 2015). "Since ISG15 is strongly induced by type I interferon, which is produced during bacterial infection, we aimed to decipher whether ISG15 is induced during Listeria infection and if so whether ISGylation acts as a means of host defense against invading bacteria." (PMID 26259872, 2015). "Recent work has indicated that ISG15 can affect mitochondrial morphology and function following Vaccinia virus infection; our identification of an enrichment of mitochondrial proteins that are ISGylated following Listeria infection is in concordance with these findings." (PMID 31772204, 2019). "If cytokine secretion in the absence of ISG15 is less efficient, it could help to explain the moderate but statistically significant susceptibility of Isg15−/− mice to systemic Listeria infection." (PMID 26259872, 2015). "Indeed, we have demonstrated that ISG15 counteracts Listeria infection both in vitro and in vivo." (PMID 26259872, 2015). "We next investigated whether ISG15 induction following Listeria infection also occurs in vivo." (PMID 26259872, 2015). "Finally, based on the results observed following TNF-α treatment, it was of critical importance to test whether a similar ISG15-dependent modulation of cytokine secretion occurred during Listeria infection." (PMID 26259872, 2015). "Our method led to the identification of 614 ISG15 sites on 292 proteins following infection in wild-type animals and 316 ISG15 sites on 219 proteins in USP18C61A/C61A animals, out of ~5000 total identified sites (18.6% of sites following Listeria infection)." (PMID 31772204, 2019). "Recently, the function of intracellular conjugated ISG15 has been extended to bacterial infections, in which it was found that Listeria infection induces ISGylation in nonphagocytic cells." (PMID 29891555, 2018). "Here, we show that in nonphagocytic cells ISG15 is dramatically induced upon Listeria infection and that, surprisingly, early induction can be type I interferon independent." (PMID 26259872, 2015). "We show that ISG15 expression in nonphagocytic cells is dramatically induced upon Listeria infection." (PMID 26259872, 2015). "Primary MEFs that lack UBE1L, and thus can not form ISG15 conjugates, have a much higher bacterial burden following Listeria infection than wild-type MEFs at 4 hr post infection." (PMID 26259872, 2015). "Here, we show for the first time, to our knowledge, that Listeria infection can lead to the direct induction of an interferon-stimulated gene, ISG15, in a type I interferon-independent manner in nonphagocytic cells." (PMID 26259872, 2015).
Listeria infection (continued). "Thus, cluster 2 (proteins present in wild-type, but absent in Isg15−/− following infection) is likely the closest approximation of the wild-type ISGylome following Listeria infection." (PMID 31772204, 2019). "If certain subsets of cells are in fact able to induce ISGs in the absence of interferon and if these ISGs like ISG15 could contribute to an antibacterial state, this may explain why these mice are resistant to Listeria infection." (PMID 26259872, 2015).
liver cancer (8 papers, 2013 to 2025). An epithelial or non-epithelial malignant neoplasm that arises from the liver. "In our early study, we found the ubiquitin cross-reactive protein ISG15 is associated with the malignant behavior of liver cancer, so we subsequently speculated the ubiquitin proteasome pathway should be abnormally activated in HCC43." (PMID 26915315, 2016). "More significantly, sorafenib non-responsive HCC patients demonstrated a notably higher expression of ISG15 in comparison to the responders, and this elevated ISG15 expression is indicative of an unfavorable prognosis among liver cancer patients." (PMID 40514377, 2025). "Therefore, further studies in HCC patients with advanced stages of liver cancer are required to correlate ISG15 mRNA expression with cancer progression." (PMID 27626177, 2016). "While interferon stimulating gene IRF9 is a key factor forcing the anti-proliferative effect of IFN-α, ISG15 is involved in a Wnt/beta-catenin suppressing pathway and may inhibit liver cancer cell growth." (PMID 25504438, 2015). "Therefore, we determined whether doxorubicin induces ISG15 expression and the formation of protein ISGylation conjugates in cell lines derived from lung, cervical, breast or liver cancer." (PMID 38443596, 2024). "Liver cancer-derived HepG2 cells but not Huh7 cells exhibited moderate induction of both ISG15 expression and protein ISGylation conjugates formation." (PMID 38443596, 2024).
Obesity (8 papers, 2017 to 2025). Accumulation of substantial excess body fat. "This minireview summarizes current knowledge on the role of ISG15 in age-related telomere shortening, genomic instability, and DNA damage accumulation, as well as in hypertension, diabetes, and obesity, major CVD risk factors prevalent in the elderly population." (PMID 37025175, 2023). "Notably, ISG15 has been recently linked to multiple mechanisms associated with aging and age-related cardiovascular disorders, encompassing heightened genomic DNA damage, telomere shortening, hypertension, type II diabetes, and obesity." (PMID 38753730, 2024). "This review discusses studies that link ISG15 to age-related telomere shortening, genomic instability, DNA damage accumulation, and three key CVD risk factors hypertension, diabetes, and obesity." (PMID 37025175, 2023). "Human studies have shown a positive correlation between plasma glucose, obesity, and Isg15 mRNA levels in peripheral blood mononuclear cells." (PMID 37025175, 2023). "In the following sections, we discuss studies that highlight an emerging role of the ISG15 pathway in hypertension, cardiac hypertrophy, diabetes, and obesity." (PMID 37025175, 2023). "ISG15 depletion in vivo promotes adipose thermogenesis and protects mice from high-fat diet-induced obesity and glucose intolerance, suggesting the role of ISG15 in the modulation of glucose metabolism and adaptive thermogenesis." (PMID 36319753, 2022). "As observed with bulk RNA-sequencing, we observed a global suppression of interferon signaling pathways with pregravid obesity across all clusters as exemplified by reduced expression of interferon-stimulated genes (IFIT3, ISG15, OAS1)." (PMID 34195568, 2021). "We observed a significant induction in the levels of C3, CP enzyme, growth factor IGFBP4, and cytokine CXCL10 and interferon signaling-related genes including (IFNβ, ISG15, MX2 and OASL2), some of which have been recognized for their role either in obesity or inflammation." (PMID 33672392, 2021). "When assessing the placental expression of factors related to viral recognition (TLR3, TLR7, and IRF3) and antiviral response (IFNs I and III, STING, RIG-I, MxA, and ISG15) from parturient with pregestational obesity (BMI ≥ 25), no changes were detected between the obese and non-obese samples." (PMID 36851534, 2023). "Moreover, Isg15-null mice had elevated energy expenditure and developed resistance to diet-induced obesity, which was attributed to lack of ISGylation of glycolytic enzymes in adipocytes." (PMID 37025175, 2023).
prostate carcinoma (8 papers, 2007 to 2025). A carcinoma that arises from epithelial cells of the prostate gland. "In prostate cancer, overexpression of ISG15 is regulated by hypoxia-inducible factors (HIF) under hypoxic conditions promoting the release of the anti-apoptotic protein Bcl2, which inhibits apoptosis." (PMID 39070493, 2024). "ISG15 and the enzymes that catalyze ISGylation and de-ISGylation are dysregulated in many types of cancer, including breast, pancreatic, and prostate cancers." (PMID 37217923, 2023). "In prostate cancer cells, covalent modification of ISG15 is weakened or inhibited to inhibit the proliferation of cancer cells." (PMID 34659576, 2021). "This is consistent with the fact that 2–5A induces the gene expression of several ISGs (P56, P54, IL8, and ISG15) in DU145 prostate cancer cells and HeLa cells." (PMID 29973937, 2018). "USP2 exhibits oncogenic potential in prostate cancer by stabilizing its substrate Fatty Acid Synthase (FAS), and FAS has indeed been identified as a target of ISG15 modification." (PMID 17653289, 2007).
Sepsis (8 papers, 2018 to 2025). Sepsis is defined as life-threatening organ dysfunction caused by a dysregulated host response to infection. "Lastly, worth noting is the fact that ISG15 mRNA expression demonstrated a positive correlation with the day of sepsis development (ISG15–day of sepsis, p = 0.035, rs = 0.42), while it tended to correlate with the day of septic shock development (ISG15–day of septic shock, p = 0.059, rs = 0.39)." (PMID 37367740, 2023). "Furthermore, ISG15 mRNA expression levels correlated positively with the day of sepsis development, while tending to correlate with the day of septic shock development." (PMID 37367740, 2023). "Since sepsis is mainly caused by bacterial infection, these results indicate that ISG15+ N03 may be a viral‐related neutrophil subpopulation in BALF but did not contribute to the sepsis immunosuppressive signature." (PMID 39887584, 2025). "Additionally, in patients who developed sepsis, EPO and ISG15 mRNA expression levels at the time of ICU admission were positively correlated." (PMID 37367740, 2023). "The aim of this study was to investigate the gene expression profile of HIF1A, ISG15, HK2, LDHA, HMOX1, EPO, and VEGFA under the setting of sepsis and septic shock, and furthermore to evaluate whether any of these molecules has potential value as a prognostic factor." (PMID 37367740, 2023).
tuberculosis (8 papers, 2022 to 2026). A chronic, recurrent infection caused by the bacterium Mycobacterium tuberculosis. "tuberculosis and highlight ISG15 or DNA leakage as promising targets for new host-directed therapies." (PMID 41738749, 2026). "This could be due to ISG15’s own cytokine properties or derived from the type one interferon signature found in active tuberculosis." (PMID 38384473, 2024). "Moreover, ISG15 mRNA is highly expressed in active tuberculosis and strongly correlates with disease severity." (PMID 38384473, 2024). "Furthermore, it has been shown in patients, as well as a mouse model of ISG15 deficiency, that extracellular ISG15 is critically involved in the production of IFN-γ that confers resistance to tuberculosis." (PMID 37614228, 2023). "Subsequently, we further verified the transcription levels of genes on anti-tuberculosis-related genes such as CCL1, IL15, IL16, ISG15, GBP5, IL23, ATG2A, IFNβ, and CSF3." (PMID 38392218, 2024). "The expression levels of certain genes related to anti-tuberculosis were further confirmed, such as CCL1, IL15, IL16, ISG15, GBP5, IL23, ATG2A, IFNβ, and CSF3." (PMID 38392218, 2024). "Rv1476 overexpression inhibited the expression of some anti-tuberculosis-related genes, such as CCL1, IL15, IL16, ISG15, GBP5, IL23, ATG2A, IFNβ, and CSF3." (PMID 38392218, 2024). "ISG15 strongly correlates with inflammation and disease severity during active tuberculosis (TB)." (PMID 35159348, 2022). "Next, we attempted to determine whether LRRC25 could inhibit the release of ISG15 in the extracellular space by mediating the degradation of ISG15 and then inhibit the release of IFN-γ to negatively regulate the anti-tuberculosis immunity of BV2 cells." (PMID 37894158, 2023). "tuberculosis in BMM, the bacterial growth was not altered by addition of extracellular ISG15." (PMID 41859120, 2026).